BLM (BLM RecQ like helicase)
Diseases named in the same sentence as BLM in open-access papers (continued):
Sharing a sentence is not in itself a finding about the gene and the disease.
Bloom syndrome (continued). "This was evidenced through the localization of BLM and TRR to UFBs in TOP3A-depleted and BS (Bloom’s syndrome) cells, respectively." (PMID 34530686, 2021). "In addition to new null alleles, we identified the first BLM variant, P868L (rs11852361), that exhibits some, but not all, defects of Bloom syndrome causing mutations and does not, based on its relatively high allele frequency, cause Bloom syndrome." (PMID 26788541, 2016). "Given that functional interactions between CAF-1 and BLM in response to replication stress are evolutionarily conserved, it is possible that the role of CAF-1 in preventing D-loop disassembly is conserved in mammals and might account for the genetic instability associated with Bloom's syndrome." (PMID 25313826, 2014). "In addition to analyzing a Bloom-syndrome-patient-derived cell line (BLM−/−, GM08505) we constructed a BLM-knockout cell line by CRISPR/Cas9-mediated disruption of BLM exon 8 in the human skin fibroblast cell line GM00637." (PMID 33495511, 2021). "BLM can displace the invading strand from the D-loop and thus can disrupt the RAD51–ssDNA filaments, which explains why BLM has also been termed an “anti-recombination” protein, which is a feature observed in Bloom syndrome (BS) patient cells." (PMID 33718381, 2021). "Moreover, the BLM HRDC domain is functionally important in double HJ dissolution, a reaction catalyzed by a BLM-topoisomerase complex that is believed to help suppress SCE, a characteristic feature of Bloom's syndrome." (PMID 29998112, 2018). "Interestingly, the recruitment of FANCM requires its direct interaction with Bloom syndrome complex composed of BLM helicase, Topoisomerase 3α, RMI1 and RMI2; as well as the helicase activity of BLM." (PMID 28058110, 2016). "NSC 19630 targets WRN helicase activity but does not affect other DNA helicases (Bloom syndrome (BLM), Fanconi anemia group J (FANCJ), RECQ1, RecQ, UvrD, or DnaB)." (PMID 27829440, 2016). "To do this, we first verified that our BLM antibody was specific by showing that it recognized a protein species that is absent in Bloom syndrome cells and in cells treated with an siRNA targeting the BLM mRNA." (PMID 25794620, 2015). "Bloom DNA helicase (BLM) combines closely with DNA topoisomerase IIIα (Top3A), RecQ-mediated genome instability protein 1 (RMI1), and RecQ-mediated genome instability protein 2 (RMI2) to form a conserved Bloom syndrome (BS) complex, which is vital for maintaining genome stability." (PMID 38007566, 2023). "Bloom syndrome results from a lack of functional BLM protein." (PMID 35359366, 2022). "Cells lacking BLM, such as those from Bloom Syndrome patients, show a much higher rate of crossovers, which can be demonstrated experimentally by the sister chromatid exchange assay, which allows exchanges of chromosome regions to be quantified by differential staining." (PMID 32369918, 2020). "Expression of wildtype BLM improved survival of Bloom syndrome cells GM08505 in the presence of HU to that of GM00637, whereas expression of P690L, R717T, W803R, Y811C, and G972V caused no improvement, suggesting that they eliminate BLM function." (PMID 26788541, 2016). "Indeed, Pml−/− MEFs show a greatly augmented frequency of sister chromatid exchange (SCE) which is a distinctive molecular feature of Bloom syndrome cell genomic instability, suggesting that the localization of BLM to PML-NB is important to ensure BLM proper function." (PMID 23847764, 2013). "Furthermore, a recent study suggests that MUS81, SLX4 and GEN1 can compensate for lack of the BLM helicase in human cells by resolving HJs in somatic Bloom's syndrome cells." (PMID 22927825, 2012).
Bloom syndrome (continued). "The lack of three coding genes BLM, WRN and RecQ4 leads to occur related diseases, which are Bloom syndrome (BS), Werner syndrome (WS) and Rothmund-Thomson syndrome (RTS), respectively." (PMID 31660888, 2019).
breast carcinoma (63 papers, 2009 to 2026). "In other studies on human subjects, the heterozygosity of BLM increases the risk and progression of colorectal cancer and breast cancer." (PMID 40728512, 2025). "A more recent meta-analysis revealed that the BLM defect common in CTE not only increases the risk of leukemia or lymphomas but also epithelial carcinomas like breast cancer." (PMID 37796556, 2023). "Smaller studies trying to link germline variants in BLM and breast cancer have yielded mixed results." (PMID 35782872, 2022). "For example, high BLM mRNA expression is associated with aggressive clinicopathological features and poor survival in breast cancer and cytoplasmic localization of BLM protein is associated with aggressive breast cancer phenotype." (PMID 35267530, 2022). "Carriers of deleterious BLM mutations are at increased risk to develop colorectal cancer and breast cancer." (PMID 35860547, 2022). "This solution was also enriched in genes known to be associated with breast cancer susceptibility (BLM, CASP8, CASP10, DNAJC1, FGFR2, MRPS30, and SLC4A7, P-value = 3 × 10−4)." (PMID 33735170, 2021). "RMI2 is also upregulated in breast cancer and SNPs in BLM and RMI1 were associated with breast carcinoma." (PMID 33662042, 2021). "BLM gene was associated with autosomal recessive Bloom syndrome, while heterozygous status was associated to breast cancer susceptibility in several studies." (PMID 31937788, 2020). "This is the largest study to date to evaluate the association between (heterozygous) mutations in the BLM gene and breast cancer." (PMID 31614901, 2019). "The finding casts doubt on the designation of BLM as an autosomal dominant breast cancer susceptibility gene." (PMID 31614901, 2019). "We identified a truncating mutation of the BLM gene in three of 617 women with hereditary breast cancer who underwent full gene sequencing." (PMID 31614901, 2019). "We analyzed loss of heterozygosity (LOH) at the BLM locus in breast cancer tissues from six women who carried a BLM truncating mutation." (PMID 31614901, 2019). "In our study, LOH analysis at the BLM locus was performed in DNA isolated from breast cancers from six BLM (p.Gln548Ter) mutation-positive women." (PMID 31614901, 2019). "Based on our study and the studies published to date, there is insufficient evidence that BLM is an autosomal dominant breast cancer susceptibility gene." (PMID 31614901, 2019). "There is clear evidence that BLM mutations in a homozygous state predispose to early onset breast cancer with a mean age of diagnosis of about 33 years." (PMID 31614901, 2019). "Although data were limited for segregation analysis, our results are consistent with the previous finding that BLM mutations are associated with a perhaps more moderate increased risk of breast cancer." (PMID 28302160, 2017). "Newer data indicate that BLM mutations contribute to breast cancer susceptibility, and heterozygous carriers of a BLM mutation have a higher probability of developing colorectal cancer." (PMID 27597923, 2016). "In two of the five families in which we identified BLM mutations one or more female relatives were indeed diagnosed with breast cancer." (PMID 26358404, 2015). "One recent study suggested that germline mutations in the BLM gene cause susceptibility to breast cancer, although the mutations are quite rare." (PMID 25945795, 2015). "Mutations in BLM that result in breast cancer were shown to be in a heterozygous state since the wild-type allele was active in the tumors." (PMID 25238049, 2014). "The rs12945597 in TOP3A and rs2532105 in BLM was significantly associated with increased breast cancer risk." (PMID 19432957, 2009). "They reported that BLM polymorphisms increased the risk of breast cancer." (PMID 38392574, 2024). "Case-control studies have shown associations between polymorphisms in BLM and breast cancer." (PMID 35782872, 2022).
breast carcinoma (continued). "However, in the case of the association of BLM mutation with breast cancer, a contradictory set of reports exists in the literature." (PMID 33777104, 2021). "Overexpression of BLM mRNA was associated with poor breast cancer-specific survival and BLM protein also influenced survival, suggesting that BLM is a promising biomarker in breast cancer." (PMID 34207556, 2021). "We found significant upregulation of ERCC6 (p = 7.95 × 10–6) and ERCC8 (p = 4.67 × 10–6) in breast cancer and similar frequencies of ERCC6 (1.8%) and ERCC8 (0.3%) mutations in breast tumors to known breast cancer susceptibility genes such as BLM (1.9%) and LSP1 (0.3%)." (PMID 33277540, 2020). "In summary, the epidemiology evidence from Eastern Europe favored the hypothesis that BLM mutations play a role in breast cancer predisposition, but other studies have led us to question this hypothesis." (PMID 31614901, 2019). "Therefore, we reasoned that BLM is a good candidate for an autosomal dominant breast cancer susceptibility gene." (PMID 31614901, 2019). "To investigate whether heterozygous carriers of a BLM mutation are predisposed to breast cancer, we sequenced BLM in 617 patients from Polish families with a strong family history of breast cancer." (PMID 31614901, 2019). "A nonsense mutation in BLM, initially been observed in few BS patients, has been associated with breast cancer in Slavic populations, and the presently available evidence for BS mutations indicates an approximately 2–5 fold increase in breast cancer risk for heterozygotes." (PMID 24025454, 2013). "The rs12945597 in TOP3A and rs2532105 in BLM showed increased risk for breast cancer." (PMID 19432957, 2009). "Furthermore, several studies reported that BLM influences the selection of the pathway for the repair of double-strand breaks in human chromosomes and that polymorphisms in BLM are associated with colorectal cancer and breast cancer." (PMID 29689049, 2018). "The high BLM expression inversely correlated with survival of breast cancer or cholangiocarcinoma patients." (PMID 37169803, 2023). "The cytosolic BLM was found previously in breast cancers, where its abundance correlated with increased aggressiveness." (PMID 37169803, 2023). "Studies have shown that overexpression of BLM, both mRNA and protein, has significant prognostic value in breast cancer." (PMID 35782872, 2022). "We tested the expression profile of USP37 and BLM in normal breast epithelium and a number of breast cancer cell lines, and found that both of them were over-expressed in the breast cancer cell lines." (PMID 34606619, 2021). "Next, we detected the expression of USP37 and BLM in human breast cancer samples by immunohistochemical (IHC) analyses." (PMID 34606619, 2021). "Controversially, BLM was reported to be overexpressed in aggressive clinicopathological breast cancer phenotypes, and also reported to be downregulated in other breast cancer subtypes." (PMID 33662042, 2021). "Knockdown of USP37 impairs the DDR through BLM and results in increased sensitivity to cisplatin or IR treatment in breast cancer cells." (PMID 34606619, 2021). "The second largest subnetwork (13 nodes) contained the two breast cancer susceptibility genes CASP8 and BLM (Section 2.6)." (PMID 33735170, 2021). "Collectively, these data suggest that overexpression of USP37 correlates with up-regulation of BLM in human breast cancer tissues." (PMID 34606619, 2021). "Taken together, these results suggest that USP37 regulates cellular response to cisplatin or IR in breast cancer cells in a BLM-dependent manner." (PMID 34606619, 2021). "We found that the mutation frequency of ERCC6 (1.8%) in breast tumors was similar to those of known breast cancer susceptibility genes, such as BRCA1 (2.9%), BRCA2 (2.9%), BLM (1.9%), FGFR2 (1.5%), and CHEK2 (1.0%)." (PMID 33277540, 2020).
breast carcinoma (continued). "The mRNA and protein expression of BLM helicase in MDA-MB-435 breast cancer cells with HJNO treatment for 24 h were examined by RT-PCR and ELISA, respectively." (PMID 31660888, 2019). "In this paper, potential antiproliferative small molecules for breast cancer were screened out from 12 small molecules (the derivatives of bisbenzylisoquinoline alkaloids tetrandrine and fangchinoline) by targeting BLM helicase." (PMID 31660888, 2019). "Studies have also shown that BLM is highly expressed in breast cancer tissue and represents a novel breast cancer biomarker." (PMID 31210839, 2019). "This also suggested that HJNO inhibited MDA-MB-435 breast cancer cells expansion by suppressing BLM helicase." (PMID 31660888, 2019). "Specific alleles of BLM have been associated with human cancers: BLM P868L (rs11852361) with colorectal cancer (odds ratio = 1.29, 95% CI, 1.02–1.64: p = 0.04) and BLM rs2532105 with breast cancer (odds ratio = 2.0, 95% CI: 1.2–3.3, p ≤ 0.05), respectively." (PMID 27413734, 2016). "The three DSB repair genes, BLM, RECQL4 and DCLRE1C, disrupted in the case group all represent attractive breast cancer susceptibility genes." (PMID 22737080, 2012). "An allele-dosage effect was found for the combination rs12945597 (TOP3A) and rs2532105 (BLM) for AML/MDS, bladder and breast cancer, where carriers with two variant alleles displayed the highest risks." (PMID 19432957, 2009). "Prostate cancer is not the only malignancy associated with increased BLM expression; similar patterns have been observed in patient samples and cell lines from colon and breast cancers." (PMID 40728512, 2025). "Moreover, the loss of function in DNA helicase genes including RECQL, BLM, WRN, RECQL5, and BRIP1 are also known to be highly correlated with the carcinogenesis of breast cancer and the BRCAness phenotype in breast cancer." (PMID 35855837, 2022). "Finally, we demonstrated that high level of USP37 mediated cisplatin or IR resistance in breast cancer in a BLM-dependent manner and clarified the role of USP37 as a potential therapeutic target in breast cancer." (PMID 34606619, 2021). "Moreover, a positive correlation between BLM and USP37 protein levels was observed in the breast carcinomas supporting a role for the activity of the USP37–BLM axis in human breast cancer cells." (PMID 34606619, 2021). "For example, 0.6% of the patients in this study had pathogenic mutations in BLM, which to date, has not been clearly associated with increased risk of breast cancer and no strategies for risk reduction have been developed." (PMID 31963545, 2020). "The following genes maybe have protective effect for the prognosis of breast cancer, BLM has a key role in homologous recombination repair, telomere maintenance, and DNA replication." (PMID 33226082, 2020). "Women with heterozygous BLM mutations should not be advised that they are at increased risk of breast cancer, and should not be counseled to intensify surveillance." (PMID 31614901, 2019). "We reviewed the pedigrees of women who have breast cancer and carry a BLM mutation and compared these with the pedigrees of breast cancer cases without a mutation." (PMID 31614901, 2019). "Clinical characteristics of breast cancers in the BLM mutation carriers and non-carriers were similar." (PMID 31614901, 2019). "The expressing BLM helicases in breast cancer cells after the small molecule treatments were examined by RT-PCR and ELISA, to explore the small molecule inhibiting cell expansion in breast cancer." (PMID 31660888, 2019). "Our robust analysis suggests that carriers of a heterozygous mutation in BLM are not at elevated risk of breast cancer." (PMID 31614901, 2019).
breast carcinoma (continued). "It is interesting that heterozygous mutations in other genes in this pathway (i.e., BRCA1, BRCA2, CHEK2, NBN, ATM) predispose to breast cancer, but a heterozygous mutation in BLM does not appear to be pathogenic for breast cancer." (PMID 31614901, 2019). "Further, we compared the clinical characteristics of breast cancers in carriers of a BLM mutation with cancers in non-carriers." (PMID 31614901, 2019). "Although the concept of increased cancer risk conferred by heterozygous mutations now seems unassailable, the evidence for specific associations between FANCC and BLM and breast cancer risk is not yet convincing." (PMID 23028381, 2012). "Furthermore, the recent largest study to date (14,804 unselected breast cancer cases and 4698 cancer-free controls) has found that heterozygous BLM mutation does not appear to increase the risk of breast cancer." (PMID 35267530, 2022). "In addition, BLM expression is also up-regulated in human breast cancer tissues." (PMID 34606619, 2021). "Our study and the studies published to date do not support the hypothesis that BLM mutations, in a heterozygous state, confer elevated risk of breast cancer (and probably of other cancers)." (PMID 31614901, 2019). "To investigate whether or not the presence of a BLM mutation increases breast cancer risk, we studied approximately 15,000 women with breast cancer and 5000 controls from Poland." (PMID 31614901, 2019). "However, as not all carriers of deleterious BLM mutations develop CRC or breast cancer, additional moderate penetrant risk factors or modifiers most likely influence cancer risk in these carriers." (PMID 26358404, 2015). "To further determine the clinical relevance between USP37–BLM axis and breast cancer, we examined the expression of USP37 and BLM in breast cancer samples." (PMID 34606619, 2021). "Assessing the individual subtypes of breast cancer, it is clear that EXO1 and BLM were, in general, much more highly expressed than in normal breast tissue, whereas Trex1 expression was usually in a similar range." (PMID 28279982, 2017). "In order to test this hypothesis we analysed in this study polymorphisms in the RMI1, TOP3A and BLM, and their association with cancer risk in available case-control materials, namely AML/MDSs (acute myeloid leukemia and myelodysplastic syndromes), malignant melanoma, and bladder and breast cancer." (PMID 19432957, 2009). "For further analysis of breast cancer, rs12945597 in TOP3A, rs401549, and rs2532105 in BLM were selected, as well as rs1563634 in TOP3A, which showed similar non-significant protective effects in all three cancer forms for the variant homozygous carriers." (PMID 19432957, 2009). "Also recently, a screen for antiproliferative drugs in breast cancer identified HJNO, a tetrandrine derivative which inhibits BLM DNA binding, unwinding and ATPase activities, diminishing breast cancer cells proliferation." (PMID 36569948, 2022). "Moreover, a positive correlation between BLM and USP37 protein levels (P < 0.0001, R = 0.536) was observed in these breast carcinomas." (PMID 34606619, 2021). "Moreover, a positive correlation between BLM and USP37 protein levels was observed in the breast carcinomas." (PMID 34606619, 2021). "BLM is overexpressed in multiple cancers, including breast cancer, however, the mechanism is not clear." (PMID 34606619, 2021). "Comparisons with non-cancer east-Asian populations and European familial breast cancer cohorts revealed significant enrichment of PALB2, BARD1, and BLM mutations." (PMID 32566746, 2020). "Briefly, in 4 families, the mutant and wildtype alleles showed exact concordance with breast cancer occurrence for variants including PALB2 and BLM, but the remaining 9 families did not perfectly match with the presence of breast or ovarian disease." (PMID 32566746, 2020).